PEX26 (peroxisomal biogenesis factor 26)
Description:
Peroxisomal docking factor that anchors PEX1 and PEX6 to peroxisome membranes. PEX26 is therefore required for the formation of the PEX1-PEX6 AAA ATPase complex, a complex that mediates the extraction of the PEX5 receptor from peroxisomal membrane.
Synonyms: FLJ20695; PBD7A; PBD7B; PEX26M1T; Pex26pM1T
Tractability: Antibody: UniProt predicts a signal peptide or a membrane-spanning region. PROTAC: its protein half-life has been measured.
Gene: Protein-coding gene on chromosome 22 (18,077,923 to 18,105,396, forward strand). Ensembl gene ENSG00000215193.
Subcellular location: Peroxisome membrane
Pathways (Reactome):
Protein localization: Class I peroxisomal membrane protein import; Peroxisomal protein import
Gene Ontology:
Molecular function: ATPase binding; protein binding; protein-containing complex binding; protein-membrane adaptor activity
Biological process: protein import into peroxisome matrix; protein to membrane docking; protein import into peroxisome matrix, receptor recycling; protein import into peroxisome membrane
Cellular component: ATPase complex; peroxisomal membrane; peroxisome; cytosol
Genetic constraint (gnomAD): Loss-of-function variants: 18 observed, 29.89 expected, observed/expected ratio (o/e) 0.6, 90% interval 0.41 to 0.89. The upper end of that interval is the gene's LOEUF score, 0.89, which puts it in group 3 of 6, group 1 being the genes least tolerant of losing a copy. Missense variants: 372 observed, 368.38 expected, observed/expected ratio (o/e) 1.01, 90% interval 0.93 to 1.1. Synonymous variants: 174 observed, 161.3 expected, observed/expected ratio (o/e) 1.08, 90% interval 0.95 to 1.22.
Gene-disease validity (ClinGen):
ClinGen rates the evidence that PEX26 causes each of these diseases.
peroxisome biogenesis disorder (autosomal recessive): Definitive.
Homologues: Orthologues: macaque PEX26 (96% identical), guinea pig PEX26 (76% identical), mouse Pex26 (75% identical), rat Pex26 (74% identical), pig PEX26 (72% identical), tropical clawed frog pex26 (33% identical), zebrafish pex26 (32% identical).
Diseases named in the same sentence as PEX26 in open-access papers:
PEX26 is named in the same sentence as 26 diseases in open-access papers, as found by Europe PMC text mining. Sharing a sentence is not in itself a finding about the gene and the disease. The quoted sentences say what the papers report.
Zellweger syndrome (8 papers, 2011 to 2025). "The expression level of FIS1 mRNA analyzed by qPCR was significant reduced (p = 0.015) in PEX26 deficient fibroblast of a patient with the severe phenotype of Zellweger syndrome (GM17398) as compared to a healthy fibroblast cell line." (PMID 34804114, 2021). "One infant was diagnosed with Zellweger syndrome with two heterozygous mutations in PEX26." (PMID 32296668, 2020). "Only 50 missense mutations (29.4%, PEX1 = 21/85, PEX6 = 27/76, PEX26 = 2/9) were reported to be associated with Zellweger syndrome, which has a severe early-lethal clinical presentation, while the remaining 70.6% of variants are truncating stop or frameshift defects." (PMID 31831025, 2019). "Approximately 80% of PBD patients are classifiedin the Zellweger syndrome spectrum, which is generally caused by mutations in the PEX1, PEX6, PEX10, PEX12, or PEX26 genes." (PMID 33912394, 2021). "The Pex26-Pex6-Pex1 complex was involved in peroxisome biogenesis disorders (PBDs), which included the Zellweger syndrome spectrum (PBD-ZSD) and rhizomelic chondrodysplasia punctata type 1 (RCDP1)." (PMID 21799737, 2011). "It has been shown by that PEX26 is responsible for Zellweger Syndrome." (PMID 37228816, 2023). "Zellweger spectrum disorders (ZSDs), including archetypal Zellweger syndrome, neonatal adrenoleukodystrophy (NALD) and infantile Refsum disease (IRD), are PBDs caused by mutations in peroxin genes (PEX1, PEX2, PEX3, PEX5, PEX6, PEX10, PEX11β, PEX12, PEX13, PEX14, PEX16, PEX19 or PEX26)." (PMID 40949164, 2025).
peroxisome biogenesis disorder (6 papers, 2011 to 2023). "Pathogenic variants in the PEX26 gene lead to peroxisomal disorders of the full Zellweger spectrum continuum." (PMID 34804114, 2021). "The genetic diagnosis was made before onset of RP in 10 young patients with apparently isolated hearing impairment: nine with Usher syndrome due to mutations in MYO7A and USH2A, and one with a peroxisome biogenesis disorder (PBD) due to compound heterozygous PEX26 mutations." (PMID 28944237, 2017). "Construction of a network of all known peroxisomal protein interactions merged with interactions identified in this study provided experimental and bioinformatic evidence for a more complex role of PEX26 in global peroxisome function as well as in pathogenesis of peroxisomal disorders." (PMID 34804114, 2021). "The diagnosis had to be reversed in the three remaining patients with apparent “atypical Usher syndrome”: They were found to have clinically similar conditions, a peroxisome biogenesis disorder (PBD; PEX26 mutations), or simultaneous presence of two non‐syndromic conditions." (PMID 28944237, 2017). "To test if the induction of peroxisomal β-oxidation by BF caused the reduction in C26:0 levels, we incubated fibroblasts from patients with a peroxisomal biogenesis disorder (PEX1, PEX6 and PEX26) with BF and measured the effect on D3-C26:0 de novo synthesis." (PMID 22447153, 2012). "Moreover, novel interactions of PEX26 with proteins involved in fatty acid metabolism has put PEX26 at the crossroads of VLCFA and plasmalogen metabolism, essential pathways for the development of brain pathology in peroxisomal disorders." (PMID 34804114, 2021).
colorectal cancer (2 papers, 2025). A primary or metastatic malignant neoplasm that affects the colon or rectum. "PEX26 expression is significantly downregulated in colorectal cancer and affects the malignant biological behaviour of colorectal cancer cells through the Wnt signalling pathway, which is associated with low OS of patients with colorectal cancer and plays a role as a tumour suppressor gene." (PMID 40995818, 2025).
Alzheimer disease (1 paper, 2025). A progressive, neurodegenerative disease characterized by loss of function and death of nerve cells in several areas of the brain leading to loss of cognitive function such as memory and language. "From the comparison of FOS exclusively defined by two questionnaires, interaction signals around peroxisomal biogenesis factor 26 (PEX26), EED, and CAMK2D were replicated in all-cause dementia, Alzheimer's disease, and vascular dementia outcomes, respectively." (PMID 40949174, 2025).
clubfoot (1 paper, 2023). The most common congenital deformation of the foot, occurring in 1 of 1,000 live births. "Mutations in peroxisomal biogenesis (PEX) factors, including PEX26, are also included in the pathogenesis of clubfoot." (PMID 37964341, 2023).
Hyperoxaluria (1 paper, 2024). Increased excretion of oxalates in the urine. "It has been associated with hyperoxaluria with NL and NC with variants in PEX1 and PEX3, likely with variants in PEX5, and possibly with variants in PEX6, PEX7, PEX10, PEX11, PEX12, PEX13, PEX16, and PEX26." (PMID 38606357, 2024). "It has been associated with hyperoxaluria with NL and NC with variants in PEX1, likely with variants in PEX5, and possibly with variants in PEX3, PEX6, PEX 10, PEX 12, PEX13, PEX14, PEX16, PEX19, and PEX26." (PMID 38606357, 2024).
hypothyroidism (1 paper, 2021). Abnormally low levels of thyroid hormone. "We found that the Pex26 protein expression level started to increase from day 15 and remained high on day 21 of hypothyroidism in comparison to euthyroid control." (PMID 34571897, 2021).
Niemann-Pick disease type C (1 paper, 2020). NPC is a complex lipid storage disease mainly characterized by the accumulation of unesterified cholesterol in the late endosomal/lysosomal compartment.
Retinal dystrophy (1 paper, 2019). Retinal dystrophy is an abnormality of the retina associated with a hereditary process. "Furthermore, at least one mutation in one patient affects the AAA-ATPase region (PEX1 and PEX6) or PEX6 binding site (PEX26) when HS patients have retinal dystrophy." (PMID 31831025, 2019).
tumor (2 papers, 2025). "have reported that disrupting the peroxisome balance by silencing PEX26 could kill drug‐resistant tumours and delay the acquisition of drug resistance." (PMID 40995818, 2025). "The expression levels of ATXN3 | chr14:92526779, LOC100130744 | chr5:14716392, METTL2A | chr17:60528133, PEX26 | chr22:18572607 and UGGT1 | chr2:128949284 in tumour tissues were significantly higher than those in normal tissues (p < 0.05)." (PMID 40995818, 2025). "The expression levels of ATXN3, METTL2A, PEX26 and UGGT1 in tumour cells were higher than those in normal mammary epithelial cells, and their expression in BRCA tissues was higher than that in normal adjacent tissues." (PMID 40995818, 2025).
metabolic disorders (1 paper, 2025). "Most PBDs patients with PEX26 mutations have metabolic disorders." (PMID 39757991, 2025).
retinopathy (1 paper, 2017). "Retrospectively, these patients had additional abnormalities (in case of PEX26‐associated PBD) or a distinct, NR2E3‐typical form of retinopathy." (PMID 28944237, 2017).
PEX26 also shares sentences with these, for which no sentence is quoted: Zellweger spectrum disorders (2 papers); breast carcinoma (1); Breast Invasive Carcinoma (1); breast tumor (1); cholestasis (1); dementia (1); Hearing impairment (1); infection (1); lymphoma (1); nyctalopia (1); rhizomelic chondrodysplasia punctata type 1 (1); Seckel syndrome (1); Usher syndrome (1); vascular dementia (1).